PPARA (peroxisome proliferator activated receptor alpha)
Diseases named in the same sentence as PPARA in open-access papers (continued):
Sharing a sentence is not in itself a finding about the gene and the disease.
diabetes (continued). "For example, the FIELD study is a multi-center, prospective, randomized clinical trial that evaluated the impact of fenofibrate, a PPARα-agonist, on cardiovascular outcomes in individuals with diabetes." (PMID 35783870, 2022). "On the other hand, in diabetes, microglia specific Pparα depletion exacerbated microglial activation." (PMID 36497130, 2022). "Activation of PPARα also prevents the progress of diabetes complications; however, its role in diabetes and cancers remains uncertain." (PMID 36589809, 2022). "PPARα overexpression in the retina of diabetic rats markedly attenuated retinal leakage and retinitis induced by diabetes, was neuroprotective and prevented the atrophy of pericytes." (PMID 35628887, 2022). "The same group further demonstrated the neuroprotective effects of PPARα activation in the retinopathy of type 1 diabetes mellitus." (PMID 34833044, 2021). "Activation of PPARα has been shown to improve lipid and glucose metabolism in diabetes by reducing hyperglycemia and increasing insulin sensitivity." (PMID 34440028, 2021). "Diabetic PPARα KO mice developed more severe DR, whereas overexpression of PPARα in the retina of diabetic rats significantly alleviated diabetes-induced retinal vascular leakage and retinal inflammation, was neuroprotective, and prevented pericyte dropout." (PMID 33581416, 2021). "PPARα is a validated target for intervention in several therapeutic areas, including inflammation, diabetes, metabolic disorders and atherosclerosis, with specific agonists isolated from natural sources." (PMID 33546180, 2021). "Although some studies demonstrated that induction of CD36 is accompanied by induction of PPARα in diabetic hearts, their induction levels vary a lot depending on various factors, including models of diabetes, used animals and the time course." (PMID 34940639, 2021). "Fibrates and other PPARα agonists that alleviate complications of diabetes elicit a range of pleiotropic effects." (PMID 33828528, 2021). "In particular, Müller glia play a key role in metabolism, express PPARα at baseline, and undergo gliosis in response to numerous stressors including diabetes." (PMID 33396512, 2020). "The PPARα agonist WY 14643 had cardioprotective effects in Goto Kakizaki rats (an animal model of diabetes mellitus type 2) upon ischemia/reperfusion manipulations." (PMID 33322384, 2020). "For example, fenofibrate, a peroxisome proliferator-activated receptor alpha (PPARα) agonist, was approved for slowing down the progression of DR in patients with type 2 diabetes mellitus in October 2013 in Australia." (PMID 32708791, 2020). "Increasing evidence suggests that PPARα activation can be a strong therapeutic target for various types of diseases such as cardiovascular diseases, dyslipidemia, and diabetes and its complications including DR." (PMID 33086679, 2020). "PPARα has been spotlighted as its expression levels have been shown to be reduced in the retinas with diabetes." (PMID 33086679, 2020). "The immense impact of PPARα on glucose homeostasis and insulin signaling is particularly well illustrated by pancreas malfunction and diabetes models." (PMID 32708786, 2020). "On a similar note, a gluten-free diet, which leads to increased expression of PPARα and PPARγ, was found to reduce diabetes incidence in NOD mice, even after exclusive exposure of the diet in utero." (PMID 32395123, 2020). "PPARα is expressed in Müller glia in humans and rats, with reduced expression in the setting of diabetes." (PMID 33396512, 2020). "Recent studies showed that diabetes reduced the expression of hepatic peroxisome proliferator activated receptor γ (PPARγ) protein and PPARα protein." (PMID 32290519, 2020). "Taurine, which stimulates PPARα, in the diet during gestation and lactation reduces diabetes development in offspring of NOD mice." (PMID 32395123, 2020).
diabetes (continued). "A previous study showed that more severe retinal acellular capillary formation and pericyte dropout were observed in PPARα−/− mice with diabetes, compared with those in diabetic wild-type mice." (PMID 33086679, 2020). "Our findings established PPARα-responsive miR-15b as a critical regulator of hepatic insulin signaling, thus serving as a new potential therapeutic target for diabetes." (PMID 30949394, 2019). "It has been shown that PPARα is decreased in the retina of experimental models of diabetes and that the PPARα knockout worsened DR." (PMID 31249556, 2019). "Further, PPARα ablation exacerbated diabetes-induced decline of visual function as demonstrated by ERG analysis." (PMID 30716067, 2019). "Pathways linked to immunometabolism were of particular interest, including type 1 and type 2 diabetes mellitus signaling, PPARα/RXRα activation, cyclic AMP (cAMP)-mediated signaling, and HIF1α signaling." (PMID 31825836, 2019). "Herein, we used fenofibrate to construct an environment in which diabetes- and high-fat diet-induced lipotoxicity can be alleviated through the activation of PPARα and AMPK." (PMID 30760777, 2019). "We established that Ex‐4 inhibited diabetes‐related activation of Rho kinase and PPARα in vivo and in vitro." (PMID 29659121, 2018). "The present study demonstrates that exendin‐4 suppresses the PPARα expression and nuclear translocation induced by diabetes mellitus." (PMID 29659121, 2018). "Unsaturated fatty acids, such as oleic acid, and agonists of PPARα enhance lipid oxidation and are expected to have therapeutic effects in diabetes." (PMID 30428888, 2018). "Peroxisome proliferators-activated receptors (PPARα, γ and δ) are potentially effective targets for Type 2 diabetes mellitus therapy." (PMID 28186999, 2017). "The thiazolidinedione troglitazone is a PPARγ agonist used as an insulin sensitizer for treatment of diabetes that also exhibits weak affinity to PPARα." (PMID 28137721, 2017). "PPARα is therefore at the cross-roads of obesity, diabetes and CVD, and thus a logical target for therapeutic intervention." (PMID 28978316, 2017). "While the pathogenesis of diabetic retinopathy is still incompletely understood, evidence suggests a role for diabetes-induced down-regulation of PPARα, as well as the involvement of inflammatory pathways, especially in obese individuals." (PMID 28978316, 2017). "It has been shown that PPARα expression is downregulated by chronic diabetes stressors and hypoxia inducible factor-1 (HIF-1)." (PMID 27069466, 2016). "PPARα hepatic activity has been shown to be potently inhibited by the stress activated JNK signalling pathway in pre-clinical model of diabetes that results in enhanced adipose tissue lipolysis." (PMID 27669233, 2016). "NF-κB plays a key role in regulating the immune response to chronic inflammatory conditions such as diabetes, and it can directly interact with PPARα to inhibit fatty acid oxidation and oxidative stress, protecting cardiomyocytes from apoptosis." (PMID 26759813, 2016). "Diabetes markedly decreased the PPARα protein levels in the db/db mice compared with that of the db/m and db/m Feno mice as assessed by Western blot analysis (P<0.01)." (PMID 24801481, 2014). "Fibrates are the most important class of drugs known to act as PPARα agonists and have been used as treatment options for diabetes and the metabolic syndrome." (PMID 25371775, 2014). "Taken together, these results demonstrate that genes centrally involved in the regulation of lipid metabolism, srebp1c, PPARγ and PPARα, Elovl4 and Elovl2 have daily rhythms of expression profile in the retina and their daily rhythms are perturbed by diabetes." (PMID 24736612, 2014). "UCP3, MCAD and PDK4 are peroxisome proliferator-activated receptor α (PPARα) targets, a transcription factor that is activated by fatty acid ligands to upregulate fat metabolism, and is increased in diabetes." (PMID 24063408, 2013).
diabetes (continued). "The objective of this study was to evaluate the potential effect of berberine on cardiomyocyte hypertrophy in diabetes and its possible influence on peroxisome proliferator-activated receptor-α (PPARα)/nitric oxide (NO) signaling pathway." (PMID 23573121, 2013). "Aleglitazar is a dual PPARα/γ agonist currently in phase III clinical development for the treatment of patients with type 2 diabetes mellitus who recently experienced an acute coronary event." (PMID 22489042, 2012). "PPARα agonists, known as fibrates, have been used for over 40 years in patients with diabetes, chiefly as lipid-lowering agents." (PMID 22448165, 2012). "Summarily, our findings support the notion that treatment of APS has a beneficial effect on lipotoxic cardiomyopathy in diabetes through a mechanism mainly dependent on the modulation of PPARα regulatory pathway." (PMID 23049681, 2012). "There is strong evidence that PPARα agonists both have independent renoprotective actions in experimental diabetes." (PMID 22448165, 2012). "Activation of PPARα with the use of fibrates in patients with diabetes increases HDL cholesterol, decreases triglyceride levels, and shifts LDL-C distribution toward larger particles." (PMID 22448165, 2012). "FAs and its derivatives act as ligands for PPARα; hence, higher cardiac PPARα activity is always observed in diabetes." (PMID 23226270, 2012). "Consistent with the known adverse effects on ACS outcome of having diabetes, homozygous −54,642 GG (wild-type) PPARA ACS patients had a 5-year mortality rate of 39.5%." (PMID 20838448, 2010). "PPARα deficiency in the setting of insulinresistance or diabetes blunts activation of FAO geneexpression, suggesting that activation of the PPARα-PGC-1α regulatory network is critical for theincreased FAO rates and lipid uptake seen in the diabetic heart." (PMID 18288281, 2008). "In PPARα-null mice with diabetes, the mean abortion ratewas approximately 50%, as compared with 8.3% for wild-type mice." (PMID 18401459, 2008). "Additionally, PPI network analysis identified key hub genes, highlighting the potential involvement of the PPARα signaling pathway in the prognosis of diabetes patients exposed to PFOS." (PMID 40137495, 2025). "It was found that the activity of PPARα was affected by the state of diabetes, and its expression and function might be inhibited, leading to lipid metabolism disorder and myocardial cell function damage." (PMID 39045049, 2024). "Fibrates are PPARα modulators used for hyperlipidemia therapy and are represented by fenofibrate and pemafibrate, whereas thiazolidinediones, such as pioglitazone and rosiglitazone, are used for the treatment of diabetes through PPARγ agonism." (PMID 37893218, 2023). "In line with our hypothesis, a study performed on mice with high-fat diet (HFD)-induced diabetes revealed that mice treated with fenofibrate (synthetic PPARα agonist) had increased concentration of SCFAs (acetate, propionate, butyrate)." (PMID 36902251, 2023). "Additionally, PPARα knockout experiments reveal that Pparα−/− rats exhibited similar outcomes to those induced with diabetes, with a significantly higher incidence of diabetic keratopathy compared to diabetic WT rats." (PMID 38004166, 2023). "Given the well-established molecular link between Sirt1 and PPARG signaling and the detrimental role played by PPARG in the context of MCM, we examined PPARG and PPARG-dependent genes LPL, PLIN, CD36, FAS and PPARA in cardiac specimens from diabetics and controls." (PMID 37957697, 2023). "PPARA activation enhances fatty acid oxidation, ketogenesis, gluconeogenesis and erythroid progenitor self-renewal, while global and liver-specific PPARA depletions lead to nonalcoholic fatty liver, diabetes and hypertension." (PMID 36555401, 2022). "Consistent with gene expression, we observed higher PPARα among patients with diabetes (p < 0.05)." (PMID 35783870, 2022).
diabetes (continued). "Interestingly, in CEA tissue, we observed that PPARα was significantly higher in patients with diabetes, and had a significant positive correlation with hemoglobin A1c and fasting glucose." (PMID 35783870, 2022). "Nevertheless, PPARα agonists show potential in diabetes treatment." (PMID 36589809, 2022). "Future studies may further explore the functions and interventions of PPARα in cancer, diabetes, immunological diseases, and neurodegenerative disease." (PMID 36589809, 2022). "For the control simulation, fenofibrate was also docked with PPARα; Fenofibrate Intervention and Event Lowering in Diabetes (FIELD) and Action to Control Cardiovascular Risk in Diabetes (ACCORD); the activation of PPARα by fibrates has rarely reduced cardiovascular disease (CV) risk." (PMID 35628280, 2022). "However, it has to be noted that the expression of PPARα is enhanced in the gastrocnemius muscle of obese mice, and PPARα is reported to be activated in skeletal muscle from type 2 diabetes mellitus patients, suggesting a possible compensatory mechanism." (PMID 35265044, 2022). "In the streptozotocin-induced diabetic rat cornea and diabetic human cornea, a decrease in PPARα expression was detected, implying that the functions of PPARα in the cornea could be impaired by diabetes." (PMID 34833044, 2021). "However, activation of PPARα does not seem to be a desirable intervention, due to similarities of constitutive cardiomyocyte-specific expression of PPARα with cardiomyopathy in diabetes." (PMID 33995129, 2021). "Cardiac PPARα is upregulated in a mouse model streptozotocin-induced diabetes." (PMID 34360540, 2021). "In experimental models of STZ-induced diabetes, PPARα, a nuclear receptor highly involved in heart metabolic processes and lipid metabolism, has been found increased in the heart of both males and females at the neonatal stage but only in that of males at the prepubertal stage." (PMID 34803741, 2021). "Thus, abnormal alteration of PPARα in response to pathological situations like diabetes and the subsequent PPAR mediated increase in fatty acid oxidation and decrease in glucose metabolism contribute to the cardiac dysfunction observed in DCM." (PMID 33397369, 2021). "The Fenofibrate Intervention and Event Lowering in Diabetes (FIELD) and The Action to Control Cardiovascular Risk in Diabetes (ACCORD) eye studies showed that fenofibrate, a well-known PPARα agonist, reduced the need for laser therapy and progression of diabetic retinopathy." (PMID 34502311, 2021). "The downregulation of PPARα protein expression by diabetes might attenuate the inhibition of PPARα on the expression of CYP450s, leading to the induction of hepatic CYP450s, which needs further investigation." (PMID 32290519, 2020). "PPARα and PPARγ are famous targets for treating diabetes, especially PPARγ." (PMID 32028670, 2020). "As these experiments were carried out in non-diabetic mice, it remains possible that local changes in PPARα may occur with fenofibrate treatment in the setting of diabetes." (PMID 33396512, 2020). "We therefore hypothesized that PPARα may improve mitochondrial function in diabetes, which would alleviate oxidative stress, energetic deficits and mitochondrial damage." (PMID 30716067, 2019). "Since PPARα has hypolipidemic and PPARγ has insulin sensitizing properties, these transcription factors have been of large clinical interest as targets for medical treatment of conditions involving cardiovascular disease and diabetes." (PMID 31308847, 2019). "Further, diabetes-induced PPARα down-regulation in the retina may contribute to retinal neurodegeneration in DR." (PMID 30716067, 2019). "However, compared with Ex‐4‐ rAAV‐GFP DM, cardiac‐restricted PPARα overexpression partly counteracted the salutary effects of Ex‐4 on diabetes‐related cardiac dysfunction, myocardial apoptosis, and oxidative stress." (PMID 29659121, 2018).
diabetes (continued). "Therefore, Ex‐4 attenuated diabetes‐induced lipid metabolic disorder mainly in a PPARα‐dependent manner." (PMID 29659121, 2018). "Besides, the PDK4 expression was increased by peroxisome proliferator-activated receptor-a (PPARa) and WY-14,643 (a potent agonist for PPARa receptor) in starvation and diabetes." (PMID 30554191, 2018). "The activation of the AMP-activated protein kinase (AMPK) system and a role of the α- and γ-peroxisome proliferator-activated receptors (PPARα and PPARγ) have been hypothesized as possible mechanisms of action for M. charantia in diabetes treatment." (PMID 29300317, 2018). "Further, decreased PPARα levels in diabetes are thought to contribute to inflammation, vascular damage, and neurodegeneration, and exogenous PPARα agonists may compensate for this effect." (PMID 25705219, 2015). "We next determined whether the expression profile of the key lipid metabolic regulator, PPARα and PPARγ, exhibited rhythmicity in the retina and liver, and whether this rhythm was impaired in diabetes." (PMID 24736612, 2014). "PPARα plays an important role in the regulation of lipid synthesis and degradation by virtue of its ability to control key transport proteins and enzymes involved in triglyceride metabolism; therefore, the PPARα signaling pathway may be impaired in diabetes." (PMID 23573121, 2013). "This study further supported that tight control of blood glucoseis beneficial for improving the fertility of diabetic women and, as clearly indicated in this study, abortion rate and neonatal mortality were increased in both wild-type and PPARα-null mice with diabetes." (PMID 18401459, 2008). "PPARγ and PPARα have similar antidiabetic and renoprotectiveeffects, therefore administration of PPARα or PPARα/γ dual agonists may be alsouseful for the prevention of kidney complications of type 1 as well as type 2diabetes mellitus." (PMID 19283081, 2008). "Notably, PPARα and PPARδ expression levels are markedly reduced in patients with diabetes." (PMID 41345744, 2025). "Here, the RNAscope assay was used to measure PPARα mRNA levels in the cornea from human donors with diabetes (13 DM, 2 females and 11 males, the average age was 68.3 y) and without diabetes (11 NDM, five females and six males, the average age was 63.5 y)." (PMID 36943878, 2023). "Soluble Klotho could inhibit the PI3K/AKT/mTORC1 signaling to upregulate peroxisome proliferator-activated receptor α (PPARα) expression by directly interacting with type 1 insulin-like growth factor (IGF1) receptor in high fat diet-fed type 2 diabetes mellitus mice." (PMID 35053218, 2022). "Moreover, a link between PPARα and diabetic renal disease became apparent after two prospective clinical trials, the Fenofibrate Intervention and Event Lowering in Diabetes (FIELD) study and the Action to Control Cardiovascular Risk in Diabetes (ACCORD) study." (PMID 35396346, 2022). "However, further research in needed to elucidate whether maternal diabetes also induces epigenetic modifications of the PPARα gene in the offspring’s heart." (PMID 34803741, 2021). "Previous studies have demonstrated that PPARα expression is down-regulated in the retinas of patients suffering from diabetes mellitus (DM), as well as in the retinas of rodents with diabetic retinopathy or oxygen-induced proliferative retinopathy." (PMID 35004756, 2021). "Therefore, the effects of GLP‐1 on PPARα expression in diabetes were explored." (PMID 29659121, 2018). "PPARα may play a particularly important role in the setting of diabetes." (PMID 26649033, 2015). "PPARα could be an important therapeutic target for maintenance of the health of the endothelium, especially with age, increased inflammation, or diseases that alter endothelial function such as diabetes." (PMID 26649033, 2015). "Indeed, overexpression of PPARα has been shown to be detrimental to cardiomyocytes resulting in impaired glucose and cardiomyopathy reminiscent of that seen in patients with uncontrolled diabetes." (PMID 25371775, 2014).